CLU (clusterin)
Diseases named in the same sentence as CLU in open-access papers (continued):
Sharing a sentence is not in itself a finding about the gene and the disease.
cancer (continued). "CLU is often overexpressed in various cancers, contributing to cell survival, evasion of apoptosis, and adaptation to stress conditions, such as hypoxia and oxidative damage." (PMID 40573993, 2025). "In this study, we present potential drug candidates targeting CLU using fragment-based drug discovery (FBDD) as potential effectors for resensitizing cancer cells to chemical treatments." (PMID 40563890, 2025). "Modulation of CLU by these factors suggests that CLU acts as a repressor in certain cancers, while in others it is essential for growth signaling and metastasis." (PMID 39253532, 2024). "This activation drives the transcriptional regulation of clusterin (CLU), resulting in the up-regulation of immune-regulatory CLU-positive cancer-associated fibroblasts." (PMID 39595558, 2024). "Conversely, a recent pan-cancer analysis by Fu and colleagues of CLU expression revealed decreased expression across most cancers compared to the matched normal tissue, including CRC." (PMID 38319453, 2024). "In this context, CLU has been studied as a potential biomarker in various types of cancer due to its tendency to be overexpressed in stressful situations." (PMID 38667280, 2024). "This suggests that CLU is regulated differently in different cancer cell types and that hypo- or hypermethylation leads to low or high CLU gene expression and different levels of sCLU and nCLU isoforms (Martindale and Holbrook, 2002)." (PMID 39253532, 2024). "CLU also protects cancer cells from apoptosis through activating class I phosphoinositide 3-kinase/PI3K-AKT pathways, and HSPA5/GRP78 activation during ER stress." (PMID 38447939, 2024). "Aging brings a multifaceted aspect to the intricate role of CLU, a versatile protein that has both deleterious effects in cancer and beneficial properties in neurological disorders." (PMID 39253532, 2024). "The assessment includes an in-depth analysis of the existing literature and examining the relationship of clusterin to fundamental aspects of cancer progression, including cell proliferation, apoptosis, metastasis, and drug resistance." (PMID 39253532, 2024). "Therapeutic approaches beyond OGX-011, such as RNA interference strategies including microRNA (miRNA), short hairpin RNA (shRNA), and small interfering RNA (siRNA), have demonstrated efficacy in suppressing CLU expression across various cancers." (PMID 38667280, 2024). "On the other hand, the proapoptotic isoform nCLU of CLU induces apoptosis in certain types of cancer, such as breast and prostate, through specific interactions with proteins like Ku70 and Bcl-XL." (PMID 38667280, 2024). "Inhibition of clusterin has been shown to be able to induce cancer cell senescence, suppress their growth and increase their sensitivity to therapy." (PMID 39253532, 2024). "Other marker genes of SFRP4+ CAFs, such as OGN and CLU, also influenced cell proliferation and invasion and cancer initiation, respectively." (PMID 38686196, 2024). "The controversial role of CLU suggests that CLU expression in various cancers is context- and signaling-dependent, with the ratio of sCLU to nCLU determining cell survival or death." (PMID 39253532, 2024). "CLU plays a pivotal role in cancer progression by modulating key processes such as programmed cell death, epithelial–mesenchymal transition (EMT), metastasis, and cell proliferation and growth through intricate signaling pathways." (PMID 38667280, 2024). "In the regulation of CLU expression during aging and cancer progression, epigenetics emerges as a pivotal player, investigating heritable changes in gene expression without altering the DNA sequence." (PMID 38667280, 2024). "Recent evidence highlights the involvement of the CLU protein in promoting cell proliferation and growth across different cancer types." (PMID 38667280, 2024). "This duality has led to recent investigations into the potential therapeutic applications of clusterin inhibition, particularly in cancer treatment." (PMID 39253532, 2024).
cancer (continued). "This review critically examines the multiple functions of clusterin in cancer and neurological disorders and addresses the controversies surrounding its role in these areas." (PMID 39253532, 2024). "As a therapeutic target, the inhibition of CLU has demonstrated excellent therapeutic effects in various cancers both in vitro and in vivo, prolonging the survival of patients." (PMID 38667280, 2024). "CLU plays a crucial role in providing chemoresistance by sequestering BAX to prevent BAX-mediated apoptosis in cancer cells." (PMID 38447939, 2024). "Select genes that were found to be associated with chemoresistance in other cancers included GDF15, THBS1, CDKN1A and CLU." (PMID 38673926, 2024). "CLU, a stress-activated cytoprotective chaperone, is upregulated in response to cancer therapies, promoting treatment resistance." (PMID 39253532, 2024). "The controversial role of CLU unfolds a complex narrative that portrays it as a double-edged sword with seemingly contradictory functions in cancer and neurodegenerative disorders." (PMID 39253532, 2024). "It is also known that silencing the CLU gene in cancer cells reduces cell proliferation and increases apoptosis." (PMID 38535120, 2024). "Chaperone proteins like CLU are pivotal in conferring resistance to cancer therapy, promoting the growth of malignant tumors and shielding drug-resistant cells." (PMID 38667280, 2024). "In this review, we discuss recent advancements in our understanding of CLU in a cancer context and its possible roles in enhancing the plasticity of regenerative stem cells in CRC." (PMID 38319453, 2024). "These insights provide a foundation for understanding the molecular intricacies of CLU regulation, offering potential avenues for therapeutic interventions in aging and cancer-related conditions." (PMID 38667280, 2024). "This explains why a significant proportion of the data on CLU regulation have been obtained in the context of cancer." (PMID 37685987, 2023). "Several studies have reported the involvement of CLU and its isoforms in various cancers, demonstrating their dual role in promoting and suppressing cancer cells." (PMID 37239129, 2023). "The differential expression of CLU in a variety of cancers highlighted the importance of CLU in cancers, and the potential of CLU as a therapeutic target." (PMID 37686218, 2023). "The combination of FDA-approved chemotherapeutic drugs with CLU inhibitors is demonstrated by these findings to be effective in treating different types of cancer, leading to improved therapeutic outcomes." (PMID 37239129, 2023). "Clusterin has been the subject of research in relation to cancer due to its participation in different aspects of the development and progression of this disease." (PMID 37834086, 2023). "Numerous roles have been assigned to CLU in regulating differentiation, proliferation, migration and survival of various cell types and cancer cells." (PMID 37685987, 2023). "One phenomenon observed in the prognosis of most cancer patients is that the CLU gene is always found to have a significant deletion in all malignancies." (PMID 37239129, 2023). "Dysregulation of clusterin (CLU) has been demonstrated in many cancers and has been proposed as a regulator of carcinogenesis." (PMID 37686218, 2023). "In our study, we found that CLU was differentially expressed among different cell populations in normal and cancer samples." (PMID 37124501, 2023). "Clusterin (CLU) is a molecular chaperone that has been linked to tumorigenesis, cancer progression and resistance to anticancer treatments, which has made it a promising drug target." (PMID 37834086, 2023). "Clusterin encoded by CLU, functions as a stress-activated molecular chaperone that is highly expressed in aggressive cancers by modulating different signaling networks." (PMID 37024866, 2023). "Most of the evidences for a cytoprotective function of CLU has resulted from analyses conducted in cancer cells (refer to Section 5 below)." (PMID 37685987, 2023).
cancer (continued). "Expression of CLU in pan-cancers was first investigated, and it was found that CLU was down-regulated in most cancers." (PMID 37686218, 2023). "This suggests that clusterin plays a protective role against apoptosis in situations of physiological stress, contributing to the acquisition of aggressive behavior in cancer, depending on the isoform expressed at that time." (PMID 37834086, 2023). "Previously, our group reported that glucocorticoids upregulate the expression of clusterin and LEDGF/p75, two oncoproteins implicated in cancer chemoresistance, in PCa cells." (PMID 37626856, 2023). "Throughout the review, we have seen the importance of the clusterin protein in tumorigenesis and cancer prognosis." (PMID 37834086, 2023). "Clusterin is a molecular chaperone that exists in various tissues and controls cancer cell proliferation through the inhibition of programmed cell death, stemness, metastasis, the EMT and therapy resistance." (PMID 36615513, 2022). "Our findings contribute to a better understanding of CLU’s role of CLU in the occurrence and prognosis of various malignant tumors." (PMID 36685863, 2022). "Clusterin is involved in a variety of processes, including adhesion, tissue remodeling, apoptosis, and cancer spread.." (PMID 36176404, 2022). "The expression of CLU was dramatically diminished in bone-metastatic cancer cells compared to their parental A549 and PC9 cells." (PMID 35626071, 2022). "Clusterin is a heavily glycosylated protein that is upregulated in various cancer and neurological diseases." (PMID 35975084, 2022). "We further retrieved datasets from The Cancer Genome Atlas and Gene Expression Omnibus to thoroughly investigate the carcinogenic consequences of Clusterin." (PMID 36685863, 2022). "This study links metformin with Clusterin for the first time and further deepens the understanding of its anti‐cancer mechanism." (PMID 36052760, 2022). "Clusterin, a glycoprotein encoded by the CLU gene, participates in EIF3I/AKT/MMP13 signaling, which facilitates cancer metastasis." (PMID 36188577, 2022). "Accumulating evidence indicates that the expression of secreted CLU correlates with the progression of cancers." (PMID 35626071, 2022). "The results of the latest preclinical studies showed that inhibition of clusterin expression delays the development of metastases and increases sensitivity to cytotoxic chemotherapy, significantly improving the survival rate of cancer patients." (PMID 36071866, 2022). "Clusterin (CLU) is a chaperone-like protein that has been demonstrated to have a direct relationship with cancer occurrence, progression, or metastasis." (PMID 36685863, 2022). "Although the role of CLU in cancer or neurological diseases has been intensively studied for three decades, the physiological functions of CLU in the context of the cardiovascular system are not as well studied." (PMID 35203598, 2022). "CLU expression positively correlates with immune cell infiltration in most cancers, including BLCA, CESC, HNSC, LGG, and PRAD." (PMID 36685863, 2022). "In conclusion, our pan-cancer study demonstrated that CLU expression is low in most malignancies and significantly correlates with clinical prognosis, DNA methylation, and immunological cell infiltration in cancer patients." (PMID 36685863, 2022). "CLU is down-regulated in the vast majority of primary and naïve cancers in comparison to normal tissue by epigenetic mechanisms that include CpG islands hypermethylation and histone tail modification." (PMID 34360868, 2021). "Our analysis showed that CLU is differentially expressed in patients according to cancer stage, race, age, nodal metastasis, and histological subtype." (PMID 33521130, 2021). "Clusterin or apolipoprotein J is a molecular chaperone involved in several pathological conditions related to oxidative stress, including neurodegenerative diseases, cancers, inflammatory diseases and aging." (PMID 33761122, 2021).
cancer (continued). "Many cancer- and inflammation-related transcription factors, as NF-κB, HIF1α, TGFβ, TNFα are involved in the transcriptional regulation of CLU during cancer progression." (PMID 34360868, 2021). "In prostate, breast, and colon cancer, the expression of CLU changes with disease progression both in the epithelial cancer cells and in the surrounding stromal tissue." (PMID 34360868, 2021). "CLU seems to promote cancer at more advanced stages of the disease, while at early stages, in agreement with our ubiquitous CLU overexpressing in vivo model, it likely exerts a suppressive role." (PMID 33744871, 2021). "Conversely, CLU expression is upregulated in the late stages of carcinogenesis, especially in niches of cancer cells resistant to chemotherapy or hormonal therapy." (PMID 34360868, 2021). "It has been reported that apoptotic triggers can upregulate CLU, which acts as a cell survival gene, and can affect cell resistance to apoptosis in carcinomas." (PMID 33521130, 2021). "The upregulation of CLU and TGFB1 genes is associated with enhanced cancer cell proliferation and anti-apoptotic properties." (PMID 32533048, 2020). "The BAMBI (Vanhara and Souček, 2013), LCN2, F13A1, CDKN2A, SLIT2, and CLU were reported to individually play a role in cancer development and progression." (PMID 33585439, 2020). "Specifically in H1975 cells, we observed a marked increase in expression of TGFB1, a known inducer of clusterin expression in cancer cells." (PMID 32533048, 2020). "Clusterin is also overexpressed in many cancers, thereby protecting cells from apoptosis induced by chemotherapy or radiotherapy, and furthermore, clusterin influences the invasion, metastasis, and transdifferentiation of tumors." (PMID 33381244, 2020). "The clusterin protein and transcript concentrations were also stimulated by small levels of ionising radiation in several rodent and human cancer cells." (PMID 32455998, 2020). "The specific role of CLU in tumorigenesis is still a matter of debate, as its expression has been found altered (i.e., upregulated or downregulated) in different kinds of cancer." (PMID 32268584, 2020). "On the whole, CLU is broadly involved in the carcinogenesis, progression, metastasis and therapeutic resistance of myriad cancers." (PMID 31540420, 2019). "siRNA-knockdown of CLU in cancer cells increases apoptosis while overexpression of CLU in L929 cells potentiates the toxicity induced by TGF-β while protecting the same cells from TNF-α cytotoxicity." (PMID 30872998, 2019). "It is of note that CLU stands as one of the major extracellular chaperones that has been extensively investigated in many cancer types." (PMID 31540420, 2019). "Here, we focus on clusterin’s role in other neurological disorders, cancer, and cardiovascular diseases." (PMID 30872998, 2019). "The silencing of CLU in human cancer cells increases apoptosis, reduces growth and increases vulnerability to oxidative stress." (PMID 30872998, 2019). "Treatment with autophagy-inducing stressors in cancer cell lines resulted in the upregulation of both clusterin mRNA and protein, which co-localized with LC3 puncta on autophagosomes’ membrane, promoting their biogenesis and increasing cell survival." (PMID 30872998, 2019). "This concept is explored further in our discussion of the role of clusterin in cancer (see section “Clusterin and Cancer”)." (PMID 30872998, 2019). "Clusterin (CLU) is a stress-activated glycoprotein, whose expression is altered both in inflammation and cancer." (PMID 31885575, 2019). "Taxane, like many anti-cancer drugs, works by promoting stress-induced apoptosis, but this is reduced in the presence of elevated clusterin levels." (PMID 30872998, 2019). "In cancer, CLU has been shown to be either up- or downregulated, although the data available on the Oncomine web site show that, in most cancer types, CLU is downregulated." (PMID 29562723, 2018).
cancer (continued). "The isoforms of CLU, secretory CLU (sCLU) and nuclear CLU (nCLU), have different roles in disease, including certain cancers." (PMID 29435130, 2018). "Alternatively, previous studies in cancer cells, suggest that effects of siRNA induced silencing or overexpression of clusterin on cell proliferation and apoptosis, are mediated via the PI3K/ AKT pathway." (PMID 29382921, 2018). "Clusterin (CLU) is a highly conserved glycoprotein expressed ubiquitously in various tissue types, and has been implicated in aging, cancer progression, and several metabolic diseases." (PMID 29435130, 2018). "Several studies have reported that clusterin played a role in anti-apoptosis by suppressing Bax in specific forms of cancer." (PMID 28767729, 2017). "Secreted clusterin is involved in cancer progression, because, as a chaperon, it protects cells from varied therapeutic stressors that induce apoptosis, including radiation, cytotoxic chemotherapy, and biologic agents." (PMID 29200898, 2017). "CLU, known as apolipoprotein J, is a secretory glycoprotein and has been reported upregulated in various human cancers, including in breast, colon, prostate and lung." (PMID 29296216, 2017). "CLU is dysregulated in multiple cancers, including gastric ones, in which overexpression seems to correlate with cancer progression." (PMID 28902909, 2017). "To confirm that the enhanced anti‐cancer activity of cabazitaxel, combined with CLU silencing, resulted from altered mitotic activity, we quantitated the number of cells displaying mitotic nuclei or multiple nuclei at various doses of cabazitaxel +/− CLU‐KD." (PMID 27198502, 2016). "Clusterin (CLU) is a stress‐activated molecular chaperone that confers anti‐cancer treatment resistance, and its inhibition potentiates the activity of taxanes in preclinical models." (PMID 27198502, 2016). "Clusterin is a secretory heterodimeric glycoprotein and the overexpression of secretory clusterin (sCLU) promotes cancer cell proliferation and reduces chemosensitivity." (PMID 26988917, 2016). "In this study we provide novel insights into the previously unexplored role of CLU in mitosis in cancer cells showing that CLU affects mitosis exit by regulating Cdc25C activity." (PMID 27198502, 2016). "In the current study, we clarified the molecular regulation and role of different CLU isoforms in cancer development by performing Y2H screening, which revealed that eIF3f is a CLU-interacting protein." (PMID 26988917, 2016). "Our data indicate that CLU silencing induces a constitutive activation of Cdc25C, which delays mitotic exit and hence sensitizes cancer cells to mitotic‐targeting agents such as taxanes." (PMID 27198502, 2016). "Recently, it was found that CLU is involved in many pathological states such as neurodegeneration and cancer." (PMID 26716898, 2016). "CLU is up-regulated in various cancers, further studies showed that CLU is regulated by oncogenes and oncoproteins." (PMID 26716898, 2016). "While CLU inhibition potentiates activity of taxanes and other anti‐cancer therapies in preclinical models, progression to treatment‐resistant disease still occurs implicating additional compensatory survival mechanisms." (PMID 27198502, 2016). "Recent clinical trials of OGX-011, an antisense oligonucleotide specifically targeting clusterin, have shown promise when combined with chemotherapy in cancer patients." (PMID 25884382, 2015). "Clusterin protein is commonly upregulated by cytotoxic chemotherapy and radiotherapy in cancer cells and contributes to cancer cell resistance in vitro and in various animal models of cancer by blocking apoptosis." (PMID 25884382, 2015). "CLU is overexpressed in several cancers and has been shown to inhibit apoptosis by interfering with Bax activation in mitochondria, while PLAGL1 is a tumor suppressor protein, which concurrently induces apoptosis and cell cycle arrest." (PMID 26573568, 2015).